NEAT1 (nuclear paraspeckle assembly transcript 1)
Diseases named in the same sentence as NEAT1 in open-access papers (continued):
Sharing a sentence is not in itself a finding about the gene and the disease.
tumor (continued). "The expression level of NEAT1 in tumor tissues of most patients is significantly higher than that of normal tissues." (PMID 33168814, 2020). "NEAT1 has been found upregulated in human GBM tissues and GBM cell line models and a high NEAT1 expression has been associated with larger tumor size, higher WHO grade, higher recurrence rate and unfavorable overall survival." (PMID 33324155, 2020). "A xenograft tumor model was established to validate the role of ATF2/NEAT1 axis in LUAD progression in vivo." (PMID 33298086, 2020). "On the other side, NEAT1 was found to promote tumor growth via inhibiting cytotoxic T cell immunity in syngeneic models." (PMID 32296457, 2020). "Despite this however, NEAT1 and by extension, the paraspeckle has also been shown to suppress tumour formation." (PMID 33143162, 2020). "In the HCC mouse models, the tumor growth was suppressed upon injection with NEAT1-silenced CD8+ T cells." (PMID 32083005, 2020). "Lastly, we verified the tumor promoting effects of NEAT1 by transducing overexpression lentivirus, which was abolished by miR-200b-3p mimic in vivo." (PMID 33202380, 2020). "The result showed that knockdown of NEAT1 by siRNA reduced tumor sphere formation induced by ADV infection." (PMID 32843056, 2020). "Results suggested that the upregulation of NEAT1 correlated with poorer differentiation, larger tumor size, later T stage, lymph node metastasis, distant metastasis and later TNM stage." (PMID 33680941, 2020). "Noteworthy, the expression levels of miR-370-3p and NEAT1 were inversely related in both GBM tumor specimens and GSCs, and a dual-luciferase reporter assay proved the direct binding between miR-370-3p and the lncRNAs NEAT1." (PMID 32443824, 2020). "NEAT1 functions as a ceRNA to promote the expression of target genes via sponging multiple tumor-suppressive miRNAs." (PMID 33298086, 2020). "Our data confirm the oncogenic role of NEAT1 and the tumor suppressor role of miR-370-3p in GBM by using patient-derived GSCs, which represent a valuable tool to obtain data to be translated onto clinical settings." (PMID 32443824, 2020). "However, the loss of NEAT1 may contribute to tumor formation." (PMID 32042268, 2020). "Tumor volume and weight were measured and results showed that downregulation of NEAT1 in ECA109 cells significantly reduced the xenograft tumor growth." (PMID 33680941, 2020). "At a molecular level, one possible mechanism by which NEAT1 exerts its oncogenic role, at least in ovarian cancer, is the interaction with the tumor suppressor miRNA miR-34a-5p, acting as a sponge and negatively regulating miR-34a expression." (PMID 32194993, 2020). "On the other hand, NEAT1 was found to inhibit cGAS-STING signaling to help cells evade T cell tumor immunity." (PMID 32296457, 2020). "In vivo, NEAT1 knockdown combined with DTX was more effective at reducing tumor growth than DTX alone." (PMID 33182737, 2020).
tumor (continued). "In accordance with these results, we reported, in HMCLs, a synergistic anti-tumor effect by combining NEAT1 silencing and the PARP (poly ADP-ribose polymerase) inhibitor olaparib, known to induce synthetic lethality in tumors with HR deficiency." (PMID 32630183, 2020). "Considering all the potential confounding factors, multivariate Cox regression analysis showed that NEAT1 expression was an independent predictor of tumour recurrence in patients with CRC." (PMID 30407674, 2019). "In terms of carcinogenesis, NEAT1 mainly functions as competing endogenous RNA (ceRNA) by sponging tumor-suppressive miRNAs." (PMID 30717168, 2019). "In this study, we found that NEAT1 expression was upregulated in CRC samples and was associated with TNM stage and poor prognosis, acting as an independent prognostic factor of tumour recurrence in patients with CRC." (PMID 30407674, 2019). "A subcutaneous LOVO xenograft model was established to observe the tumour growth activity affected by NEAT1 knockdown." (PMID 30407674, 2019). "MTT, colony formation, flow cytometry, transwell assays and a xenograft tumour model were used to assess the functions of NEAT1." (PMID 30407674, 2019). "When the tumours were harvested, the average volumes and weight in sh‐NEAT1 group were decreased compared with sh‐NC group." (PMID 30407674, 2019). "A significant upregulation of NEAT1 was observed in tumor tissues of BC patients by several previous studies." (PMID 30803129, 2019). "The expression of a number of miRNAs, including known tumor suppressor miRNAs (let-7a and miR-34a) and miR-361, was markedly upregulated in NEAT1-knockdown SPAC-1-L cells." (PMID 31287002, 2019). "We showed that NEAT1 functions as an oncogenic sponge for the tumor suppressor microRNA-361 (miR-361), which suppresses proliferation, invasion, sphere formation and TX resistance by directly targeting the oncogene STAT3." (PMID 31287002, 2019). "Mechanistically, NEAT1 serves as a molecular sponge for miR-361, a pivotal tumor suppressor that suppresses proliferation, invasion, sphere formation and TX resistance by directly targeting the oncogene STAT3." (PMID 31287002, 2019). "Inhibiting NEAT1 expression with small hairpin RNAs (shRNAs) diminished cellular proliferation, invasion, sphere formation, and xenograft tumor growth and improved TX response in aggressive EC cells." (PMID 31287002, 2019). "Having investigated the tumour promoting effects of NEAT1 on CRC cells in vitro, we further checked its effect in vivo." (PMID 30407674, 2019). "In vivo experiment further validated the inhibitory effects of NEAT1 knockdown on xenograft tumour growth." (PMID 30407674, 2019). "In one recent study, NEAT1 suppressed miR-335 expression and facilitated tumor growth and invasion via disinhibition of MET." (PMID 31645479, 2019). "NEAT1 has been suggested to function as an oncogenic sponge in EC where it sequesters several tumor suppressor miRNAs (miR-146b and miR-214) to activate the WNT/β-catenin pathway." (PMID 30781521, 2019). "Using the xenograft tumour model, we evidenced that knockdown of NEAT1 inhibited CRC tumour growth in vivo." (PMID 30407674, 2019). "We then drew the survival and recurrence curves, which showed that the CRC patients with NEAT1 high expression had shorter survival and higher tumour recurrence as compared to those with NEAT1 low expression." (PMID 30407674, 2019). "Colony formation induced by overexpression of E1A;HRasV12 is also promoted in MEF cells derived from Neat1 KO mice, which produced larger tumours when transplanted subcutaneously." (PMID 30355755, 2018).
tumor (continued). "The expressions of NEAT1 in OS tissues were analyzed and the roles of NEAT1 in tumor growth and chemotherapy resistance were determined by knockdown or overexpression in vitro and in vivo." (PMID 29654165, 2018). "Knockdown or depletion of HOTAIR, LOC100507661, NEAT1 as well as overexpression of NAMA can inhibit tumor progression." (PMID 29416703, 2018). "The enrichment analysis showed that NEAT1 influenced multiple biological processes, including cell–cell adhesion, which plays pivotal roles in tumor cell proliferation and metastasis." (PMID 30154460, 2018). "Knockdown of NEAT1 via small interfering RNA or short hairpin RNA inhibits the malignant behavior of tumor cells." (PMID 30374364, 2018). "Overexpressed NEAT1 inhibited the tumor suppressor miR-34c, promoted the survival of OS cells, inhibited apoptosis, and reduced the sensitivity to DDP in vitro and in vivo." (PMID 29654165, 2018). "Four OS cell lines MG63, 143B, HOS, and Saos2 cells and one human osteoblastic cell line hFOB1.19 cells were used and we confirmed that the NEAT1 level was up-regulated in tumor cells when compared with that in normal cells." (PMID 29654165, 2018). "The lncRNA NEAT1 is abnormally upregulated in somatic malignancies and has been found to promote tumor growth in CRC." (PMID 30185232, 2018). "We found that the expression of miR-34c was down-regulated in OS tissues and negatively correlated with the expression of NEAT1 in tumor tissues." (PMID 29654165, 2018). "The impaired tumor growth rate of sh-NEAT1 tumors was completely rescued in mice injected with DAG+FFA." (PMID 29764424, 2018). "NEAT1 have been demonstrated to be up-regulated in various human malignancies and functions as oncogene in most solid tumor via sponging of tumor-suppressive miRNAs." (PMID 29654165, 2018). "NEAT1 activated the transcriptional activity of β-catenin to promote CRC tumor progression in a DDX5-mediated manner." (PMID 30185232, 2018). "Our results suggest that NEAT1 promotes CRC tumor growth and metastasis by stabilizing the DDX5 protein, thereby activating β-catenin gene transcription." (PMID 30185232, 2018). "The results showed that the mice treated with DDP and NEAT1-knockdown MG63 cells had the slowest tumor growth than that treated with DDP alone." (PMID 29654165, 2018). "Among the eight down-regulated genes, one is an oncogene (NEAT1), six are tumor-suppressor genes (ASS1, PTPRD, ISG15, TGFBI, SELENBP1, MEG3) and one gene serves as both an oncogene and tumor-suppressor gene (CDH17)." (PMID 30563222, 2018). "We here collected OS tissues (n=40) and adjacent non-tumor tissues (n=20) to determine the expression of NEAT1 and its clinical significance." (PMID 29654165, 2018). "A number of cohort studies report correlation between NEAT1 expression and altered tumour progression or poor prognosis." (PMID 30355755, 2018). "In vivo studies also confirmed that knockdown of NEAT1 sensitized tumor cells to cisplatin/paclitaxel- or radio-induced tumor regression." (PMID 30374364, 2018). "NEAT1 was overexpressed in OS tissues, which positively correlated with tumor size, Enneking stage, and distant metastasis of OS patients." (PMID 29654165, 2018). "Identifying the upstream and downstream targets of NEAT1 will elucidate its critical role in tumor progression." (PMID 30185232, 2018). "Both datasets showed that NEAT1 expression was significantly upregulated in the tumor tissues compared to the levels in the normal tissues." (PMID 30185232, 2018). "Recent studies manifested that NEAT1 contribute to the tumor progression through its regulation of diverse cellular processes, including migration, invasion, proliferation, differentiation, and apoptosis." (PMID 29026116, 2017). "The results indicated that the expression of NEAT1 was higher in the tumor tissues than the corresponding normal issues." (PMID 28507281, 2017).
tumor (continued). "In short, NEAT1 over-expression exerts a tumor-suppressor effect, and there is negative regulation between NEAT1 and miR-101-3p." (PMID 29050268, 2017). "Meanwhile, NEAT1 was related to tumor differentiation, invasion and metastasis in colorectal cancer." (PMID 28751672, 2017). "The effect of NEAT-1 on modulation of EZH2 expression further supports an effect of this lncRNA on tumor growth." (PMID 28122578, 2017). "In the future, well designed larger-sample studies and better design studies will be necessary to verify and strengthen the prognostic role of NEAT1 in neoplasm patients." (PMID 29026116, 2017). "The high expression of NEAT1 in the tissue and whole blood of CRC patients is associated with tumor differentiation, invasion, metastasis and TNM staging." (PMID 28108736, 2017). "The authors discovered that NEAT1 was highly expressed in tumor tissue, and an enhanced expression of NEAT1 stimulated the proliferation of ESCA cells and promoted their ability to form foci, migrate, and invade." (PMID 28118609, 2017). "Specifically, NEAT1 expression was remarkably higher in larger tumors and at later stages of tumor development." (PMID 27351135, 2016). "Up-regulation of NEAT1 promoted tumor cell proliferation, and down-regulation of NEAT1 inhibited tumor cell proliferation." (PMID 27351135, 2016). "NEAT1 acts as an oncogene to promote tumor progression in NSCLC in large part attributed to its ability to inhibit miR-377-3p (acting as “competitive endogenous RNAs (ceRNAs)”) and subsequent activation of the E2F3 signaling pathway." (PMID 27351135, 2016). "On the other hand, Pten plus the large non-coding RNAs Malat1 and Neat1 were among the 80 down-regulated genes with mRNA processing, nuclear bodies, ER-stress response and tumor suppression as relevant terms." (PMID 27801298, 2016). "Among them, 49 cases (~75%) showed significantly increased level (>1.5‐fold) of NEAT1 in tumor tissues compared with their normal control, whereas only 10 cases (~15%) showed down‐regulated NEAT1 level (>1.5‐fold) in OC samples." (PMID 27075229, 2016). "And miR-377-3p treated xenograft tumors from pGCMV/NEAT1 cells showed decreased tumor growth in vivo compared with xenograft tumors from pGCMV/NEAT1 cells." (PMID 27351135, 2016). "Our study indicated that increased expression of NEAT1 lncRNA in GACs correlated with tumor stage as well as lymph node metastasis in clinical GAC samples." (PMID 26911892, 2016). "The average tumor weight in NEAT1 siRNA-treated LSCC xenografts was significantly lower than that in the control group (1.085 ± 0.132 g versus 2.487 ± 0.160 g, P < 0.01)." (PMID 26822763, 2016). "By transmission electron microscopy, we observed typical apoptotic morphology in the tumor cells in NEAT1 siRNA treated group, characterized by homogeneous condensation of chromatin to one side or the periphery of the nuclei." (PMID 26822763, 2016). "Kaplan–Meier analysis of overall mortality revealed that patients with high tumor NEAT1 expression have a significantly poorer outcome when compared with patients with low tumor NEAT1 expression (P=0.005, hazard ratio 1.22 95% confidence interval=1.06–1.41)." (PMID 25417700, 2015). "The postoperative median disease-free survival time of patients with tumor of low NEAT1 expression was 50 months (95% CI cannot be estimated) while that of patients with tumor of high NEAT1 expression was 28 months (95% CI: 22–34)." (PMID 26314847, 2015). "The tumour growth was monitored weekly for 45 days and was found to be significantly lower in the NEAT1 shRNA-expressing group compared with the control group." (PMID 25415230, 2014).
tumor (continued). "We computed the log2-fold change of expression levels using the 13 paired tumour/benign samples for NEAT1 and for these selected genes." (PMID 25415230, 2014). "In both these experiments, a significantly higher tumour growth was seen in the NEAT1-overexpressing cells further confirming its oncogenic potential." (PMID 25415230, 2014). "We confirmed the efficacy of the shRNA in vivo by measuring the NEAT1 and ERα levels in the tumours." (PMID 25415230, 2014). "NEAT1 promoted tumor growth and metastasis through the action of DDX5." (PMID 41244835, 2025). "Additionally, NEAT1 was found to raise the miR-129 gene’s DNA methylation, which inhibits the tumour suppressor miR-129-5p expression in breast cancer." (PMID 40730640, 2025). "Collectively, M2‐TAM‐derived exosomal NEAT1 promoted HCC tumor growth in mice." (PMID 39720765, 2025). "Additionally, the level of CD8 in tumor tissues was significantly reduced by M2‐exo treatment, whereas this change was eliminated by NEAT1 knockdown." (PMID 39720765, 2025). "If tumor cells highly express the “don't eat me” signaling, NEAT1‐31 might have an ineffective outcome." (PMID 40344649, 2025). "In addition to miRNA, several lncRNAs, including HOTAIR, MALAT1, TUG1, and NEAT1, play crucial roles in regulating gene expression and significantly impact tumor progression." (PMID 40806675, 2025). "Additionally, NEAT1 expression was significantly lower in patients with T3 and T4 tumor stages compared to those with T1 and T2 stages (median: 0.38 vs. 0.43; p = 0.041)." (PMID 40150019, 2025). "By employing CRISPR-Cas9 to inhibit NEAT1 expression, the sensitivity to radiation of the radiation-resistant cells were found to be increased that resulted in reduced cell multiplication, expression of tumor stemness markers like SOX2, BMI1, and OCT4." (PMID 39912983, 2025). "It was postulated that NEAT1 affects LC aggressiveness by promoting metastasis and tumor growth." (PMID 40150019, 2025). "The development of small molecule inhibitors or antagonists targeting molecules like ENO1, LIN28b, UCA1, and NEAT1 may be effective in inhibiting tumor growth and metastasis." (PMID 40384875, 2025). "It is interesting to note that some lncRNAs such as HOTAIR, ANRIL, GAS5, NEAT1, CCAT2, UCA1 are consistently reported to be associated with several prognostic indicators such as advanced FIGO stage, increased tumour growth, lymph node metastasis and lowered survival measures." (PMID 39912983, 2025). "Furthermore, NEAT1 drives tumor cell proliferation and migration via the miR-153-3p/Wnt/β-catenin axis and the miR-204/NUAK1 axis." (PMID 40723840, 2025). "For instance, the lncRNA NEAT1 is a hypoxia-inducible lncRNA critical for the formation of paraspeckles, which can sequester RNA transcripts and transcriptionally active proteins, thereby modulating the expression of proteins involved in tumor metastasis." (PMID 39940704, 2025). "Given the fact that NEAT1 overexpression is sufficient to promote cell growth, colony formation, as well as invasive migratory ability in a tumor type–specific manner, diminished NEAT1_1 could contribute to part of these downregulated pathways." (PMID 39032650, 2024). "Moreover, the authors concluded that the tumor progression is due to the influence of NEAT1 on the miR-26a/b-5p/STAT3 axis by sponging the miRNA, which increases YKL-40 expression." (PMID 39188680, 2024). "Recently, the lncRNA NEAT1 was shown to regulate glycolysis to accelerate tumor progression." (PMID 38733179, 2024).